IL6 (interleukin 6)
Diseases named in the same sentence as IL6 in open-access papers (continued):
Sharing a sentence is not in itself a finding about the gene and the disease.
Anxiety (continued). "Similarly, another study found an association between the levels of diverse cytokines present in CSF of patients with dementia, discovering that anti-inflammatory interleukin-6 (IL-6) cytokine levels were inversely proportional to anxiety scores in AD patients." (PMID 34099005, 2021). "There is evidence that depressive and anxiety symptoms in the early puerperium in fare causally related to an increased catabolism of Trp into KYN, which may be associated with increased plasma levels of IL-6." (PMID 34072767, 2021). "Similarly, the IL-6/IL-10 ratio reflected a negative association with anxiety related to Relationship with Spouse/Partner (p < 0.01)." (PMID 34360332, 2021). "Certainly, any of the psychosocial dimensions of anxiety can develop into chronic stress if not addressed; Preparation for Labor and Relationship with Spouse/Partner were of particular interest due to their association with IL-6/IL-10 and TNF-α/IL-10 ratios." (PMID 34360332, 2021). "Therefore, our research hinted that EGCG might suppress the level of IL‐6 by downregulating STAT3 pathway as well as inhibit apoptosis of hippocampal neuron by decreasing the level of IL‐6, thereby alleviating the anxiety‐like behavior after MI." (PMID 32304289, 2020). "Furthermore, in terms of the pro-inflammatory phenotype shift that is linked to HPA-axis dysregulation, upregulation of inflammatory markers such as interleukin -6 (IL-6) has been reported in the context of trauma, with similar findings in anxiety related research." (PMID 32298279, 2020). "The network showed that interleukin 6 (IL-6) and tumor necrosis factor (TNF) were most associated with the DE mRNAs and miRNAs, which suggested that inflammatory factors might play an important role in chronic pain with anxiety." (PMID 32655622, 2020). "Interestingly, decreases in hippocampal TNF and IL-6 levels were observed in a murine eCM model with cannabidiol treatment, which also increased brain derived neurotrophic factor levels, promoted eCM survival and prevented post-CM anxiety-like behaviours." (PMID 32703204, 2020). "The authors found that chronic administration of IL-6 mAb prevented the development of social avoidance, which they considered a marker of susceptibility to stress consequences, while it failed to reduce anxiety-like behavior induced by stress in the EPM." (PMID 30557308, 2018). "In addition, IL-6 was shown to be involved in the inhibition of neurogenesis and the development of hyper-excitable neurological conditions including epilepsy, psychoses, anxiety, and autism spectrum disorders in experimental models." (PMID 26842664, 2016). "Within-group analyses showed that anxiety severity correlated negatively with MiR-34c and positively with Tau, Aβ, MDA, IL-6, and VILIP-1." (PMID 42052788, 2026). "However, random forest machine-learning models suggested that depressive symptoms (HADS-D) might be linked to inflammatory cytokines (IL-6, IL-23) and metabolic indicators (waist circumference, HOMA-IR, FIB-4), whereas anxiety symptoms (HADS-A) showed weaker and less consistent associations." (PMID 41601492, 2026). "Biomarkers (cortisol and IL-6), neuropsychological tests (TMT and Stroop test), ophthalmological parameters (contrast sensitivity), sleep (polysomnography), and anxiety." (PMID 40995183, 2025). "Ethanol exposure increased anxiety and immobility in behavioral tests, consistent with depressive-like behaviors, and elevated TNF-α, IL-1β, and IL-6 levels." (PMID 40860877, 2025). "GD dams exhibited weight and glucose reduction, pancreatic IL-6 elevation, GLUT3 reduction, astroglia changes in the cerebral cortex, gut barrier impairment, cognitive impairment, and heightened anxiety compared to controls." (PMID 40243881, 2025).
Anxiety (continued). "In the multivariate logistic regression analysis, which included IL-6, CRP, ESSPRI total, ESSPRI pain, ESSPRI fatigue, and ESSDAI, only ESSPRI fatigue was identified as an independent predictor of anxiety (OR = 1.99, 95%CI: 1.12-3.53, P = 0.019)." (PMID 40822847, 2025). "Our findings indicate that psychological status, including anxiety and OCS, correlates with levels of IL-6 and IL-8, even after adjusting for confounding factors." (PMID 39757257, 2025). "The results show a significant correlation between anxiety behavioral indicators and CORT levels, inflammatory factors (IL-6, IL-1β, CD86, TNF-α, TGF-β, IL-10), 5-HT, and GABA." (PMID 40078708, 2025). "Both T2DM and cancer are characterised by elevated secretion of proinflammatory cytokines (e.g., IL-6, TNF-α, IL-1β), which can cross the blood–brain barrier and activate microglia, thereby contributing to depressive and anxiety symptoms." (PMID 41149069, 2025). "Cytokine Inhibitors: Targeted therapies such as IL-6 inhibitors (e.g., tocilizumab) and TNF-α blockers have shown promise in reducing anxiety symptoms in patients with high inflammatory markers." (PMID 40218134, 2025). "rhamnosus LB1.5 resulted in a decrease in serum IL-6 levels in HFD-fed mice and promoted a reduction of anxiety-like behavior, as assessed in the LDB test." (PMID 38542789, 2024). "The peripheral rise in corticosterone in the first 3 h of LPS exposure promote the increase in IL-1β, IL-6, and TNF-α, exerting an anxiety effect on the limbic system, including the hippocampus." (PMID 39057053, 2024). "We assessed lifespan, motor performance using balance and coordination tests, cognitive function through anxiety and memory tests, redox markers, and inflammation markers, particularly TNF-α and IL-6." (PMID 39656492, 2024). "At the end of the study, HFFD resulted in anxiety‐like behavior, reduced locomotor activity, neuroinflammation (increased brain GFAP, IL‐6, MCP‐1, IFN‐γ, TNF‐α), and systemic inflammation (increased plasma GFAP, IFN‐γ, TNF‐α, IL‐12p70, reduced plasma IL‐10)." (PMID 39619979, 2024). "Genetic models of T2D, such as the db/db mice, also showed anxiety-like behavior, increased levels of inflammatory cytokines (IL-1β, TNF-α, and IL-6), and reduced levels of BDNF in the hippocampus." (PMID 38279738, 2024). "rhamnosus LB1.5 supplementation decreased serum IL-6 levels in HFD-fed mice and promoted a reduction in anxiety-like behavior." (PMID 38542789, 2024). "Based on the previous studies and our current findings, it can be suggested that synbiotics appear to have anxiolytic effects on anxiety by regulating TNF‐α and IL‐6 levels, which are effective in anxiety formation." (PMID 39264256, 2024). "From the perspective of the mechanism of sugar on anxiety, on the one hand, sugar intake may participate in the neuroinflammatory process in brain regions by changing the levels of inflammatory factors such as IL-6, TNF-α, leptin, and iNO, leading to excessive production of nitric oxide." (PMID 39479195, 2024). "A few studies have correlated anxiety symptoms with increased cytokine levels, including CRP and IL-6." (PMID 36757901, 2023). "This is consistent with findings that indicated IL-6 and IL1B levels were elevated in depressive-like behavior and anxiety." (PMID 37623226, 2023). "Consistent with previous studies, we also observed that LPS markedly increased the expression of TNF-α, IL-Iβ, and IL-6 in the PFC and peripheral serum, inducing depressive-like and anxiety-like behaviors." (PMID 35573384, 2022). "For instance, minocycline, an antibiotic with anti-inflammatory properties, reduced the level of IL-1, IL-6 and TNF-α and ameliorated anxiety behaviors after trauma exposure." (PMID 35625844, 2022). "Pretreatment with losartan significantly improves FST performance and prevents LPS-induced anhedonia and anxiety-like behaviors in addition to preventing LPS-induced higher levels of the pro-inflammatory cytokine (TNF, IL-1, and IL-6)." (PMID 36761172, 2022).
Anxiety (continued). "As pro-inflammatory cytokines can influence anxiety- and depressive-like behaviors, we analyzed the expression of TNF, IL-6, and IL-1β in the hippocampus." (PMID 36333302, 2022). "The evidence from human studies shows a close relationship between prenatal exposure to pro-inflammatory cytokines, such as TNF-α, IL-1β, IL-6, IL-17a, and ASD, schizophrenia, anxiety, depression, and ADHD." (PMID 35937892, 2022). "In this line, the levels of IL-6 and TNF-α, two major pro-inflammatory cytokines, have shown to be noticeably related to the severity of anxiety." (PMID 35949300, 2022). "Compared to VILI mice treated with α-IL-6 antibody, the VILI mice treated with saline spent significantly less time in the center area, indicating increased anxiety, avoidance, and mood alterations (p = 0.032)." (PMID 36100846, 2022). "Oxidative stress upregulates angiotensin-1 receptor levels and elevates NF-κB-mediated pro-inflammatory factors levels (IL-6, TNF-α) in these brain areas, leading to anxiety-like behaviors." (PMID 36761172, 2022). "Results for sex-stratified MR analyses suggested that higher IL-6 could be a risk factor for depressive symptoms specifically for women while higher CRP could be protective for depressive symptoms specifically for men and for anxiety symptoms specifically for women." (PMID 34505025, 2021). "Furthermore, we have carried out one- and two-sample MR analyses to test whether associations of IL-6 and CRP with specific depressive and anxiety symptoms are likely to be causal using genetic variants regulating levels/activity of these inflammatory markers as instrumental variables." (PMID 34135474, 2021). "In our present study, both peripheral and central IL-1β, IL-6, and TNF-α levels were significantly increased after CFA injection, and the injected mice showed obvious anxiety-like behaviors." (PMID 32019580, 2020). "Significantly increased gene expression of Il-1β and Il-6 in SAMP8 control in comparison with SAMR1 mice was determined, confirming the inflammatory phenotype related to anxiety- and depressive-like behaviours presented by SAMP8." (PMID 32456135, 2020). "LPS-induced acute-sickness behavior, including anxiety- and depressive-like behavior was prevented by attenuating among TNF-α, IL-1β, and IL-6 levels of brain and plasma of mice." (PMID 31213027, 2019). "Thus, it is probably that the sooner locomotion recovery of CD1 mice compared to BALB/c could be related with their lower anxiety status and their higher IL-6 concentrations, although other inflammatory mediators such as prostaglandins and leukotriens could be also involved with wellness." (PMID 30133465, 2018). "The abnormality rates of IL-6, IL-8, TNF-α and CRP in both the BD group and the atypical BD group were all significantly higher than those in the simple anxiety group (P < 0.05)." (PMID 29065864, 2017). "In the present study, we confirmed that early treadmill exercise improved anxiety‐like behavior and learning and memory and induced decreases in glial cells and proinflammatory cytokines (PAF, IL‐6, TNF‐α, ICAM, and VCAM) activation." (PMID 29201553, 2017). "The presence of associations between both IL-6 and TNF and investigatory behavior suggest that interactions between these two cytokines may mediate initial social investigation, possibly through changes in anxiety and aggression related responses to social interaction." (PMID 28753980, 2017). "TNF‐α was elevated in the hippocampi of the anxiety groups, IL‐6 and TNF‐α were also significantly increased in the plasma of the subjects with signs of anxiety." (PMID 29201553, 2017). "Unlike basal inflammation, LPS-stimulated inflammation was stillassociated with (anxiety) symptom severity after adjustment for lifestyle and health(IDS: IL-8, MCP-1, MMP2; BAI: LPS index, IL-6, IL-8, IL-10, IL-18, MCP-1, MMP2,TNF-β)." (PMID 27244234, 2016).
Anxiety (continued). "Inescapable footshock with SRs induced anxiety and cognitive dysfunction as well as a decrease in the levels of plasma H2S and GSH and an increase in IL-6 levels in 3×Tg-AD mice." (PMID 26635562, 2015). "An increase in inflammatory markers such as IL-1, IL-6, TNF-alpha, and IFN-gamma have been documented in ADs including PTSD, PD, and OCD as well as anxiety-related personality traits such as neuroticism." (PMID 25390645, 2014). "Of interest, all groups exhibited increased anxiety, while injured and blast noise-exposed rats showed elevated corticosterone, interferon-c (IFN-c), and interleukin-6 (IL-6) in the amygdala and hippocampus." (PMID 24312074, 2013). "Our findings are supported by a previous study demonstrating that AGOM treatment decreased the release of cytokines (TNF-α, IL-6 and IL-1β) and restored BDNF levels and the activity of the antioxidant enzymes CAT and GPx in the brain in an HFD-induced anxiety-like behavior model." (PMID 40076566, 2025). "A 2025 Chinese case control study demonstrated that interleukin-6 concentrations were significantly higher in PPD patients and correlated (r = 0.48) with concurrent anxiety scores; machine-learning classifiers using cytokine panels achieved 86% accuracy in identifying anxious–depressed phenotypes." (PMID 40731779, 2025). "In contrast, the intervention group with FD but without anxiety had significant reductions in IL-6 and TNF-α (p < 0.05), along with a significant decrease in the PAGI-SYM score (p < 0.001)." (PMID 40606168, 2025). "CUS/UCS protocols (especially those of 10–15-day duration) exhibited the strongest construct and predictive validity, consistently inducing persistent anxiety-like phenotypes, social avoidance, and neuroendocrine changes (e.g., elevated cortisol and altered BDNF, IL-6 expression)." (PMID 40427646, 2025). "They found that anxiety predicted lower levels of metalloproteinase-9 (β = −.38, p = .03) but did not predict levels of interleukin-1 or interleukin-6." (PMID 40392872, 2025). "Notably, inhibition of IL-6 by MP5 antibody treatment increased the locomotor activities of STAg mice at the open field arena’s center, suggesting amelioration of anxiety-like behaviors (STAg + IgG vs. STAg + MP5, p < 0.0001)." (PMID 41150800, 2025). "In addition, SCFAs can modulate microglia activation, influencing the release of pro-inflammatory factors, such as IL-1β, IL-6, and TNF-α, which can further impact neuroinflammation and anxiety-like behaviors." (PMID 41459223, 2025). "Furthermore, it has been shown that exercise reduces inflammatory markers, such as C-reactive protein (CRP), interleukin-6 (IL-6), and TNF-α, thus reducing chronic inflammation-triggered anxiety symptoms." (PMID 41144483, 2025). "In our study, we observed elevated levels of IL-6 and anxiety scores in first-line medical staff compared to non-first line medical staff, consistent with previous research." (PMID 39757257, 2025). "In contrast, chronic stress protocols extended from 7 days to up to 11 weeks and consistently produced enduring anxiety-like behaviors, social impairments, and molecular alterations such as increased cortisol, dysregulated CRF/BDNF/IL-6 expression, and oxidative stress signatures." (PMID 40427646, 2025). "Through a larger production of inflammatory cytokines, including C-reactive protein and interleukin 6, visceral adipose tissue may play a significant role in the link between BAI and ABSI and anxiety and stress." (PMID 38811944, 2024). "The elevation of these cytokines (especially IL-1β, IL-6, IL-10, IFN-γ, and TNF-α) may have a role in stress and anxiety in infected patients." (PMID 39935742, 2024). "Based on PPI network analysis, AKT1 and IL-6 might be the crucial target genes for the overlapping pathology of PTSD and anxiety." (PMID 37986356, 2023).
Anxiety (continued). "Our findings demonstrate that those reporting myalgia, low mood, and anxiety at follow‐up had lower admission IL‐6, CRP, and ferritin respectively, than those without these symptoms in the group that survived." (PMID 37904690, 2023). "A positive correlation was detected between anxiety and serum ferritin, IL-6, MCV, and MCH levels, and a negative correlation between the corona anxiety score and RBC count." (PMID 37016651, 2023). "As a control, neither the pain threshold nor the anxiety-like behaviors were changed in IL-6–deleted mice." (PMID 36917193, 2023). "Due to the known relationships between these parameters and anxiety on the one hand and itch on the other hand, the link between anxiety and PSO-itch could be mediated by SP, IL-6 and IL-17." (PMID 36928456, 2023). "High TNF-α (P=0.002, adjusted P=0.008), but not high IL-1β (P=0.864, adjusted P=1.000), IL-6 (P=0.160, adjusted P=0.640), and IL-17 (P=0.266, adjusted P=1.000), was correlated with anxiety occurrence." (PMID 35239774, 2022). "In addition, it was found to improve communication, stereotyped movement, anxiety-like behavior, and sensorimotor behavior in ASD model mice, as well as reduce the increased expression of IL-6." (PMID 36090083, 2022). "In fact, alteration in redox balance, increased reactive oxygen species (ROS) production and high circulating inflammatory cytokines such as interleukin (IL)-1, IL-6, and tumor necrosis factor (TNF) have been detected both in anxiety patients and stressed animal models of anxiety." (PMID 36077225, 2022). "Furthermore, in a rat model of LPS-induced anxiety, honey had protective effects against anxiety by decreasing the expression levels of TNF-α and IL-6." (PMID 36358502, 2022). "Overall, IL-6 signaling may represent a molecular pathway that is common to the pathogenesis of VILI, delirium-, and anxiety-like behaviors, and explain why these neuropsychiatric impairments occur so commonly as a sequela of VILI." (PMID 36100846, 2022). "In addition, a red pomegranate fruit extract-based formula ameliorated anxiety-like behaviors through reducing the levels of serum inflammatory cytokines NF-κB, TNF-α, IL-6, IL-1β and IFN-γ." (PMID 36358502, 2022). "As it pertains to prospective associations between inflammatory markers and anxiety symptoms during adolescence, a study investigated 39 inflammatory markers (including TGF-α, IL-6, and TNF-α) without any significant findings." (PMID 35360574, 2022). "Cohort studies of affective symptoms also suggest that circulating IL-6 and CRP concentrations are predominantly associated with depressive rather than anxiety symptoms." (PMID 34505025, 2021). "For the total study population, HADS anxiety scores showed a negative correlation with IL-4 and IL-6 (p ​= ​.021, ρ ​= ​−0.184; and p ​= ​.023, ρ ​= ​−0.182)." (PMID 34589849, 2020). "For healthy controls, anxiety was correlated with stimulated IL‐6 (r = 0.295, P = 0.040) but not with any other laboratory measures of inflammation." (PMID 31199593, 2020). "Moreover, humans experimentally treated with LPS display increased anxiety as well as increases in IL-6 and TNF-α, 2 to 3 hrs thereafter, being the changes in IL-6 more pronounced involved in their anxiety status." (PMID 30133465, 2018). "The chemokines or inflammatory cytokines such as IL-6 and TNF-α production in MRL/lpr mice may be involved in anxiety behaviors." (PMID 25093033, 2014). "ZSSF treatment dramatically reduced anxiety-like behaviors, exerted sedative–hypnotic effects, increased hippocampal 5-HT and 5-HTP, and enhanced intestinal barrier function through inhibiting colon ZO-1, Claudin-1, and Occludin expression and reducing TNF-α, IL-6, and IL-1β levels." (PMID 40077533, 2025). "Therefore, suitable clinical intervention on the anxiety may have potential benefits in MSA by monitoring the serum TNF-α and IL-6 levels." (PMID 39295596, 2024).